TNF (tumor necrosis factor)
Diseases named in the same sentence as TNF in open-access papers (continued):
Sharing a sentence is not in itself a finding about the gene and the disease.
Pancytopenia (20 papers, 2008 to 2025). An abnormal reduction in numbers of all blood cell types (red blood cells, white blood cells, and platelets). "The LASSO combined with 5-fold cross-validation identified 13 significant features from the candidate variables, as follows: maximum temperature, duration of fever, serum sodium, TG, HDL, LDH, ferritin, CRP, FIB, PT, TNF-α, pancytopenia, and liver damage." (PMID 38725078, 2024). "In January 2016, the TG was stopped after the patient had been established on anti-TNF therapy for 12 months combined with recurrent episodes of pancytopenia." (PMID 32917155, 2020). "The main complications of immunosuppressive agents included adenitis with azathioprine (n = 1), zoster infection with anti-TNF alpha therapy (n = 1) and pancytopenia under azathioprine (n = 1)." (PMID 25213625, 2014). "While low plasma ADA2 levels and elevated TNFα are diagnostic markers for DADA2, immunological screening is essential to avoid delays, especially when pancytopenia is the sole clinical presentation in disorders that impact both marrow cell development and immune function." (PMID 40975757, 2025). "Pancytopenia and aplastic anemia were observed rarely during TNF-α inhibitor treatment." (PMID 34640327, 2021). "Since rare cases of pancytopenia, and very rare cases of aplastic anemia, some of which with fatal outcome, have been reported in patients treated with anti-TNF, caution should be used in patients receiving treatment with anti-TNF who have a history of blood dyscrasias." (PMID 38979406, 2024). "We subjected Perf1 KO mice to infection with MCMV, which induces IFN-γ and TNF-α and observed that these mice indeed developed a lethal condition similar to HLH, with pancytopenia, hemophagocytosis in the bone marrow and severe inflammation in the liver and spleen." (PMID 22891066, 2012).
scleritis (20 papers, 2012 to 2026). Inflammation of the sclera. "In conclusion, we identified the association of various TNF gene related haplotypes with scleritis in Chinese Han, including TGT in TNFAIP3, GT in TNFSF4, and CCC in TNFSF15." (PMID 33287909, 2020). "Literature reviews of anti-TNFα drugs also reference cases of ocular malignancy, herpes zoster keratosis, scleritis, necrotising fasciitis, retinal vein occlusions, optic neuritis, and de novo or relapse of existing chronic uveitis." (PMID 39767762, 2024). "Recent clinical observations suggested a decreasing incidence and severity of scleritis in RA, which was attributed to the use of modern therapies, including biologics such as TNFα-inhibitors." (PMID 38983001, 2023). "TNF-α is the major active component of TNF, accounting for 70%-95% of the total, and several studies have shown that TNF-α participates in the pathogenesis of scleritis." (PMID 37063831, 2023). "It was found that TNF was the highest-scoring hub gene in all scleritis subtypes, TNF and IL6 and their targeted drugs remained applicable to non-infectious scleritis and anterior scleritis." (PMID 37063831, 2023). "The significance of TNF in the context of sight-threatening ocular surface diseases in RA patients, such as peripheral ulcerative keratitis and scleritis, was demonstrated through the clinical improvement observed after administering infliximab treatment." (PMID 37876547, 2023). "In summary, the evidence supporting the critical role of TNF-α in scleritis provides a basis and rationale for TNF-α-targeting treatment." (PMID 36431163, 2022). "The key role of TNF-α in the pathogenesis of inflammatory diseases has been emphasized in previous studies, which provides the basis for anti-TNF-α agents for treating scleritis." (PMID 36431163, 2022). "In fact, among the various reports of molecularly targeted therapies for scleritis, those describing the efficacy of TNF inhibitors are the most common." (PMID 35008766, 2021). "Ten weeks after introducing CTLA4Ig, the patient was switched to golimumab (GLM), a TNF inhibitor, by the department, and scleritis rapidly disappeared within one month." (PMID 35008766, 2021). "The fact that marked infiltration of macrophages into the sclera was seen in our mouse model of scleritis suggests that TNF and IL-6, as cytokines produced by macrophages for innate immunity, represent appropriate target molecules." (PMID 35008766, 2021). "Certolizumab pegol has been shown to control scleritis in a patient with RA who had failed other TNF-α antagonists." (PMID 22229035, 2012). "Moreover, matrix metalloproteinases (MMPs) contributes to scleral destruction, and their production can be induced by TNF-alpha, which is found in the tissues of some scleritis patients." (PMID 40038580, 2025). "These cytokines target macrophages, and from the results of analysis of the CIA scleritis model in this study, it is possible that inhibition of IL1, IL-6, and TNF might also be effective in suppressing scleritis." (PMID 35008766, 2021). "Anti-TNF-α agents have the most evidence supporting their use and efficacy in scleritis." (PMID 22229035, 2012). "Escalation to biologic disease-modifying antirheumatic drugs (bDMARDs), specifically tumor necrosis factor-alpha (TNF-α) inhibitors and rituximab (RTX), is supported for refractory scleritis and corneal melt, although evidence is largely observational." (PMID 42122940, 2026). "Among the biologics used, the tumour necrosis factor (TNF)-α inhibitor ADA was the most frequently prescribed, with scleritis being the most common condition treated." (PMID 41288845, 2025). "The efficacy of TNF-α inhibitors in non-infectious uveitis and scleritis has been demonstrated, which likely explains these results." (PMID 41288845, 2025). "There have been several studies that have highlighted the benefits of anti-tumor necrosis factor (anti-TNF) in the management of non-infective scleritis secondary to GPA." (PMID 39759718, 2024).
scleritis (continued). "TNF and IL6 are considered key mediators and possible drug targets of scleritis." (PMID 37063831, 2023). "Eighty-eight potential drugs were considered as candidates for the key genes TNF and IL6, and DALIMUMAB, ETANERCEPT, INFLIXIMAB, PF-04236921, and INSULIN were found to act against both TNF and IL6 and were identified as potentially contributing to the treatment of scleritis." (PMID 37063831, 2023). "Monoclonal antibodies against TNF-α (all except Etanercept), IL-1 inhibitors (Anakinra), IL-6 inhibitors (Tocilizumab), and anti-CD20 (Rituximab) targeted-drugs have been shown to control inflammation and reduce scleritis flares, allowing for a corticosteroid-sparing effect." (PMID 38060142, 2023). "In addition, TNF-α elevates the level of MMPs, which may disrupt the balance between MMPs (MMP3 and MMP9) and TIMPs and induce scleritis." (PMID 35756002, 2022). "Moreover, histocompatibility complex (MHC), TNF, IL1A, IL1β, IL2, IFNγ, and TNF were widely present in the top five disease signaling pathways, suggesting that these genes may be involved in the development of scleritis." (PMID 37063831, 2023). "Although various reports have described the use of molecularly targeted therapies using biologics such as TNF inhibitors, IL-6 inhibitors, CTLA4Ig, anti-CD20 antibody, and anti-CD25 antibody, the optimal molecules to target with molecularly targeted therapy in scleritis have remained unknown." (PMID 35008766, 2021).
vivax malaria (20 papers, 2006 to 2022). "A study of a population in the Brazilian Amazon that was similar to our population found that one TNF haplotype (TNF-1031T/-863A/-857T/-308G/-238G) including the TNF-308G allele was associated with increased susceptibility to mild vivax malaria." (PMID 25038626, 2014). "Although DDX39B and TNF genes are near each other on the same chromosome and appear to influence the transcription of its gene products, this study did not identify a haplotype with DDX39B (22C > G and 348C > T) and TNF-308G > A polymorphisms that increased the risk of clincal vivax malaria." (PMID 25038626, 2014). "In addition, the genotype combinations GC/CC/GG/GG and GG/CT/GG/GG, corresponding to the respective polymorphisms DDX39B-22/DDX39B-348/TNF-308/IL6-176, were associated with a decreased or increased risk, respectively, of developing mild vivax malaria, probably by altering TNF and IL-6 levels." (PMID 25038626, 2014). "Previous studies have associated the role of BAT1 as an anti-inflammatory gene in diseases such as Chagas cardiomyopathy and Plasmodium vivax malaria through the modulation of tumor necrosis factor-alpha (TNF-α) and interleukin-6 (IL-6)." (PMID 36505884, 2022). "The SNPs were assessed regarding association with systemic levels of TNF, IL-6, CXCL10, and CRP, which have been associated with vivax malaria manifestations." (PMID 25038626, 2014). "The aim of this study was to investigate the relationship between single nucleotide polymorphisms (SNPs) in the DDX39B, TNF and IL6 genes and the clinical outcomes of patients with Plasmodium vivax malaria." (PMID 25038626, 2014). "SOD-1 was a more powerful predictor of disease severity than TNF-alpha in individuals with different clinical presentations of vivax malaria." (PMID 20386593, 2010). "The findings of this study provide support that the C allele of DDX39B-22C > G is a risk factor of complicated vivax malaria, and different haplotypes (including DDX39B and TNF polymorphisms) may influence disease outcomes by altering plasma levels of TNF." (PMID 25038626, 2014). "Given the major role of the host immune system in P. vivax infection, the aim of this study was to determine whether mutations in the DDX39B, TNF and IL6 genes were associated with the clinical outcomes of patients with vivax malaria." (PMID 25038626, 2014). "SOD-1 protein levels were more effective at predicting vivax malaria severity than TNF-alpha." (PMID 20386593, 2010). "Furthermore, SOD-1 has a higher sensitivity than TNF-alpha in predicting severe vivax malaria, indicating also a higher likelihood ratio to discriminate this clinical condition." (PMID 20386593, 2010). "In an attempt to address if the plasma levels of both SOD-1 and TNF-alpha were useful to discriminate P. vivax from P. falciparum malaria, we compared plasma samples from individuals presenting with mild symptomatic vivax malaria and age matched individuals with symptomatic P. falciparum infection." (PMID 20386593, 2010). "Furthermore, highly secreted pro-inflammatory cytokines, IL-6 and TNF, in vivax malaria patients represent T cell differentiation toward Th2 and Th17 may be skewed and trigger the natural acquisition of cellular memory immune responses." (PMID 34183015, 2021). "Furthermore, we showed that the predominantly anti-inflammatory cytokine response in clinical vivax malaria was short-lived, with IL-10 concentrations and IL-10/TNF-α, IL-10/IFN-γ and IL-10/IL-6 ratios all returning to within the normal range found in non-infected controls after chemotherapy." (PMID 22973442, 2012). "Herein, TNF-α concentrations were found to be significantly reduced in coinfected individuals, when compared to both HBV or symptomatic vivax malaria patients." (PMID 31233500, 2019). "Liver enzymes are highly inducible by the activation of immune responses and ALT was also correlated with TNF and superoxide dismutase-1 (SOD-1) levels in another case series of vivax malaria." (PMID 26271921, 2015).
vivax malaria (continued). "It was observed that TNF-α, IL-10, ICAM-1 and VCAM-1 were the 4 best individual predictors of complicated vivax malaria with AUROC of 0.89 (95% CI: 0.84 - 0.94), 0.79 (95%CI: 0.73- to 0.86), 0.63 (0.55-0.71) and 0.84 (95% CI: 0.78- 0.90) respectively." (PMID 24324686, 2013). "The sharp increase in TNF-α levels preceding febrile paroxysms in vivax malaria can elicit the release of soluble TNF-α receptors, which in turn regulate TNF-α activity." (PMID 22973442, 2012). "Because IL-10 regulates the production and function of inflammatory cytokines, we computed IL-10/TNF-α, IL-10/IFN-γ and IL-10/IL-6 ratios and found a bias toward regulatory cytokines in clinical vivax malaria." (PMID 22973442, 2012). "In predicting severe vivax malaria, SOD-1 levels exhibited higher sensitivity than TNF-alpha (80% vs. 56%, respectively; p<0.0001; likelihood ratio: 7.45 vs. 3.14; p<0.0001)." (PMID 20386593, 2010). "When compared to symptomatic vivax malaria patients, coinfected individuals presented elevated levels of IFN-γ, IL-10 and CCL2, and diminished plasma concentrations of multiple variables as TNF-α, IL-6, IL-12, and CRP." (PMID 31233500, 2019). "Patients with HBV monoinfection presented the same number of variables which concentrations were increased (mainly IFN-γ, TNF-α, IL-6 and CXCL9), when compared to asymptomatic vivax malaria monoinfection, but only significant decrease of one variable (also IL-4)." (PMID 31233500, 2019). "In the present study and not surprisingly, IFN-γ and TNF and the chemokine CCL5 were demonstrated to be crucial biomarkers in the network profile of those individuals with mild vivax malaria." (PMID 23433077, 2013).
acute monocytic leukemia (19 papers, 2010 to 2025). Acute monoblastic leukemia (AML-M5), is one of the most common subtypes of acute myeloid leukemia (AML) that is either comprised of more than 80% of monoblasts (AML-M5a) or 30-80% monoblasts with (pro)monocytic differentiation (AML-M5b). "For instance, it has been shown that BA inhibits the production of TNF-α induced by lipopolysaccharide in human acute monocytic leukemia cells." (PMID 37772231, 2023). "In vitro, after IL-38 overexpression, the levels of IL-6, IL-23, and tumor necrosis factor-α (TNF-α) in human acute monocytic leukemia cell line (THP-1) were decreased." (PMID 34539413, 2021). "The ethyl acetate extract of M. emarginata at a concentration of 50 μg mL−1 effectively inhibited TNF-α production (IC50 of 5.9 μg mL−1) in lipopolysaccharide (LPS)-induced human acute monocytic leukemia cells (THP-1)." (PMID 34685875, 2021). "Graphene oxide and vanillin-functionalized graphene oxide induce pro-inflammatory cytokines in a human acute monocytic leukemia cell line, and PtNPs dose-dependently induce cytokines such as IL-1β, IL-8, and tumor necrosis factor alpha (TNFα)." (PMID 31936679, 2020). "We measured the concentration of TNF-α released by human acute monocytic leukemia cells (THP-1) in the presence of rLj-HMGB1." (PMID 22563397, 2012). "Tumour necrosis factor alpha (TNFα) increased CCR9 expression on human acute monocytic leukemia cell line THP-1 monocytic cells." (PMID 20738854, 2010). "To assess whether apoC-I modulates innate immune responses by human cells, we assessed the effect of apoC-I on IL-6 and TNF-α expression by the human acute monocytic leukemia cell line THP-1." (PMID 22883744, 2012). "Moreover, KO exhibited potent anti-inflammatory activity, suppressing tumor necrosis factor-α (TNF-α) secretion in both lipopolysaccharide (LPS)-stimulated human acute monocytic leukemia cells (THP-1) and rat peritoneal macrophages, with consistent efficacy in mice inflammation models." (PMID 40822403, 2025). "We further revealed that Lj-HMGB1 was able to induce the production of tumor necrosis factor-α (TNF-α), a pro-inflammatory mediator, in activated human acute monocytic leukemia cells." (PMID 22563397, 2012). "Additionally, phloridzin limits TNF‐α mRNA and IL‐8 expression, thereby suppressing CXCL10 production in LPS‐stimulated human acute monocytic leukemia cell lines." (PMID 40761486, 2025). "According to pre-clinical research, after silencing PCSK9 expression with siRNA, significant reduced IL-1α, IL-6, and TNF-α expression, as well as downregulated activation of the NF-κB pathway, were observed in human THP-1 (an acute monocytic leukemia cell line) cells." (PMID 40872487, 2025). "GSK3β-siRNA knockdown diminished expression of TNF-α in LPS(UO)-stimulated RAW 264.7 macrophages, inhibited NF-κB activation, enhanced CREB activation in LPS(UO)-stimulated acute monocytic leukemia THP-1 cells, and diminished expression of IL-1β, IL-6, and TNF-α in WNV infected HGC U251 cells." (PMID 34017345, 2021). "Meanwhile, P. pinaster EO (α-pinene 62%) did not inhibit LPS-indued TNF-α and CCL2 production in human acute monocytic leukemia cells (THP-1)." (PMID 35744988, 2022).
alcohol abuse (19 papers, 2013 to 2025). The use of alcoholic beverages to excess, either on individual occasions ("binge drinking") or as a regular practice. "Activation of TNF-α has been associated with impaired neuronal functioning and increased risk of alcohol abuse and relapse." (PMID 39624490, 2024). "Patients with documented alcohol abuse have elevated plasma levels of tumor necrosis factor alpha (TNF-α), a molecule that induces inflammation." (PMID 41517547, 2025). "For instance, a recent study found that patients with alcohol use disorders had a significant increase in IL-6 concentrations but a reduction in TNF-α approximately 3 h after acute alcohol ingestion." (PMID 37760011, 2023). "Alcohol abuse can trigger the formation of endotoxins and activate Kupffer cells, thereby generating the pro-inflammatory factors tumor necrosis factor-alpha (TNF-α) and interleukin-6 (IL-6)." (PMID 35685625, 2022). "According with our experimental results, human studies have also shown that alcohol abuse during human pregnancy induces upregulation of cytokines (IL-1β, IL-6, and TNF-α) in both maternal blood and fetal cord levels at delivery." (PMID 28738878, 2017). "Indeed, studies on patients with alcohol use disorder have demonstrated a positive correlation between craving for alcohol and levels of pro-inflammatory cytokines (such as TNF-α and IL-6)." (PMID 36009076, 2022). "Thus, alcohol abuse seems to increase TNF-α levels and may theoretically explain a possible lack or loss of response to IL-17 blockers, as with secukinumab in our EP patients." (PMID 31159169, 2019). "Alcohol abuse activates TLR4-related signaling pathways, leading to systemic inflammation and increased TNF-α production." (PMID 41194914, 2025).